A3GALT2 (alpha 1,3-galactosyltransferase 2)
Description:
Synthesizes the galactose-alpha(1,3)-galactose group on the glycosphingolipid isoglobotrihexosylceramide or isogloboside 3 (iGb3) by catalyzing the transfer of galactose from UDP-Galactose to its acceptor molecule Gal-beta-1,4-Glc-ceramide. Can also catalyze the addition of galactose to iGb3 itself to form polygalactose structures.
Synonyms: iGb3S; A3GALT2P; IGBS3S
Tractability: Antibody: UniProt predicts a signal peptide or a membrane-spanning region.
Gene: Protein-coding gene on chromosome 1 (33,306,766 to 33,321,098, reverse strand). Ensembl gene ENSG00000184389.
Subcellular location: Golgi apparatus, Golgi stack membrane
Gene Ontology:
Molecular function: alpha-1,3-galactosyltransferase activity; glycosyltransferase activity; N-acetyllactosaminide 3-alpha-galactosyltransferase activity; hexosyltransferase activity
Biological process: glycosphingolipid biosynthetic process; carbohydrate metabolic process
Cellular component: Golgi apparatus; vesicle; Golgi cisterna membrane; membrane
Genetic constraint (gnomAD): Loss-of-function variants: 17 observed, 16.64 expected, observed/expected ratio (o/e) 1.02, 90% interval 0.7 to 1.53. The synonymous counts are far from expectation, so gnomAD's model fits this gene poorly and the ratio says little. Missense variants: 600 observed, 381.73 expected, observed/expected ratio (o/e) 1.57, 90% interval 1.47 to 1.68. Synonymous variants: 253 observed, 160.19 expected, observed/expected ratio (o/e) 1.58, 90% interval 1.42 to 1.75.
Homologues: Orthologues: chimpanzee A3GALT2 (98% identical), macaque A3GALT2 (92% identical), dog A3GALT2 (83% identical), rabbit A3GALT2 (81% identical), guinea pig A3GALT2 (78% identical), mouse A3galt2 (69% identical), rat A3galt2 (68% identical). Paralogues in human: ABO (38% identical), GBGT1 (34% identical), GLT6D1 (28% identical).
Diseases named in the same sentence as A3GALT2 in open-access papers:
A3GALT2 is named in the same sentence as 5 diseases in open-access papers, as found by Europe PMC text mining. Sharing a sentence is not in itself a finding about the gene and the disease. The quoted sentences say what the papers report.
melanoma (1 paper, 2022). A malignant, usually aggressive tumor composed of atypical, neoplastic melanocytes. "The Gal-pHLIP therapeutic efficacy was tested in immunized A3galt2 knockout mice using a B16F10 melanoma tumor model." (PMID 36686229, 2022).
A3GALT2 also shares sentences with these, for which no sentence is quoted: Fabry disease (1 paper); neuropathic pain (1); pancreatic tumor (1); tumor (1).